BAP1 (BRCA1 associated deubiquitinase 1)
Diseases named in the same sentence as BAP1 in open-access papers (continued):
Sharing a sentence is not in itself a finding about the gene and the disease.
pancreatic cancer (continued). "A recent study confirmed the activity of BAP1 in HR on the basis of a GFP-based reporter assay; loss of BAP1 caused a substantial reduction in the DNA repair rate in pancreatic cancer cells." (PMID 37009801, 2023). "Although over 80% of familial pancreatic cancer cases harbor mutations in BRCA1/2 and ATM, germline deletion and mutations of BAP1 have also been observed." (PMID 32541668, 2020). "Heterozygous mice also develop pancreatic cancer suggesting a haploinsufficient tumor suppressor role for BAP1." (PMID 32541668, 2020). "Other malignancies instead express normal levels of BAP1: for example BAP1 is expressed and detected by IHC in most pancreatic carcinomas, and in most peritoneal and gynecologic serous adenocarcinomas." (PMID 27447750, 2016). "Interestingly, 50% inhibitory concentration (IC50) assessment indicated that BAP1 deletion sensitized pancreatic cancer cells to the treatment of IRAK1/4i." (PMID 40083694, 2025). "Similarly, overexpression of BAP1 in the BAP1-low-expressing pancreatic cancer cell line SW1990 also resulted in a consistent phenomenon." (PMID 40083694, 2025). "To verify this hypothesis, we knocked out BAP1 using two independent single-guide RNA in two human pancreatic cancer cell lines with relatively high BAP1 expression, PaTu8988 and CFPAC-1." (PMID 40083694, 2025). "Intrigued by this finding, we sought to investigate whether BAP1 similarly regulates cancer immunity, using pancreatic cancer as our working model." (PMID 39350280, 2024). "After observing the antagonistic relationship between BAP1 and SIRT1, particularly in their convergence on the K80 acetylation of HSF1, we became intrigued by the potential efficacy of combining SIRT1 inhibition with ICB therapy in models of pancreatic cancer characterized by BAP1 deletion." (PMID 39350280, 2024). "Given that heterozygous loss of BAP1 is the most frequent somatic aberration among DNA repair genes in pancreatic cancer, our findings establish a rationale for evaluating BAP1 status to stratify patients who are likely to respond to FOLFIRINOX and radiotherapy." (PMID 32541668, 2020). "Heterozygous loss of BAP1 was also present in (a) 40% of ACC, which also exhibit copy number losses for several DNA repair genes, and (b) 15–20% of pancreatic tumors arising from mucinous cystic neoplasms (MCNs), intraductal papillary mucinous neoplasms (IPMNs), and solid pseudopapillary neoplasms." (PMID 32541668, 2020). "Rarely, our institutions may test for CDKN2A or BAP1 as a single test, particularly if other cancers, such as pancreatic cancer or astrocytoma in the family, strongly suggest CDKN2A is the offending gene." (PMID 28283772, 2017). "We subsequently examined whether BAP1 regulates the expression of PD-L1 in pancreatic cancer cells." (PMID 39350280, 2024). "Thus, downregulation of BAP1 alleviates a barrier to pancreatic cancer progression, but at the same time its low expression maintains basal DNA repair mechanisms protecting rapidly dividing cancer cells from the catastrophic consequences of uncontrolled accumulation of DNA damage." (PMID 32541668, 2020). "To delve deeper into the mechanism by which BAP1 regulates pancreatic cancer’s response to immunotherapy, we analyzed transcriptome data from the TCGA-PAAD dataset, comparing patients with BAP1 deletion to those with diploid or amplified BAP1 expression." (PMID 39350280, 2024). "Moreover, we generated control and Bap1 knockout KPC (KrasG12D/+; LSLTrp53R172H/+; Pdx-1-Cre) mouse pancreatic cancer cell lines and established the mouse syngeneic subcutaneous pancreatic cancer model." (PMID 39350280, 2024). "Similarly, BAP1-null mouse and human pancreatic cancer cell lines were sensitive to IR and failed to form colonies when plated at low densities." (PMID 32541668, 2020).
pancreatic cancer (continued). "Interestingly, we observed a positive correlation between BAP1 expression and the level of tumor-infiltrating immune cells, including CD8+ T cells, NK cells, CD4+ T cells, macrophage, neutrophil and dendritic cells, but not Myeloid-derived suppressor cells in pancreatic cancer tissues." (PMID 39350280, 2024).
ovarian carcinoma (13 papers, 2015 to 2025). A malignant neoplasm originating from the surface ovarian epithelium. "Her mother had a family history of breast and ovarian cancer but was herself healthy and tested negative for variants in HBOC genes as well as the BAP1 variant." (PMID 35381901, 2022). "We hypothesized that BAP1-mutant mesothelioma might be addicted to PARP1-mediated DNA repair pathways, similar to the BRCA1/2-mutant breast and ovarian cancers." (PMID 28756516, 2017). "We hypothesized that BAP1-mutant MPM would require PARP1 for survival, similar to the BRCA1/2 mutant breast and ovarian cancers." (PMID 28756516, 2017).
bladder cancer (12 papers, 2017 to 2025). "Here, we report a germline nonsense BAP1 variant (c.850G>T, p.Glu284Ter) in a patient with bladder cancer and a strong family history of malignancy." (PMID 32218990, 2020). "With the addition of bladder cancer to the tumor types reported with germline BAP1 mutations, our understanding of the BAP1 TPDS continues to evolve, and may affect future screening and surveillance guidelines." (PMID 32218990, 2020). "Genes like BAP1 and ATM showed high biallelic loss in kidney and bladder cancers." (PMID 40420266, 2025). "Five of the 26 SMGs had not been reported as SMGs in bladder cancer in previous studies: CDKN1B (1.2%), ITK (1.8%), PRDM2 (3.1%), FOXA1 (2.7%), and BAP1 (1.8%)." (PMID 36495164, 2023).
non-small cell lung carcinoma (12 papers, 2015 to 2024). A group of at least three distinct histological types of lung cancer, including non-small cell squamous cell carcinoma, adenocarcinoma, and large cell carcinoma. "All 45 non-small cell lung cancer biopsies stained positive for nuclear BAP1, whereas 22/35 (63%) MM biopsies lacked nuclear BAP1 staining, consistent with previous data." (PMID 27447750, 2016).
epithelioid mesothelioma (11 papers, 2017 to 2025). "In particular, epithelioid mesotheliomas exhibit the highest prevalence of BAP1 mutations, which is reported in up to 60% of cases." (PMID 41463268, 2025). "The loss of immunohistochemical expression of BAP1 helps to make the correct diagnosis in many cases in which the differential diagnosis is between epithelioid mesothelioma and reactive hyperplasia." (PMID 35204459, 2022). "Immunohistochemical staining confirmed the presence of tumor cells (panCK-positive) that histologically matched the patient diagnosis of BAP1-positive epithelioid mesothelioma, across all three conditions." (PMID 40568242, 2025). "BAP1 mutations can be detected in 45%–100% in MPM, and are mainly present in epithelioid mesothelioma, which is associated with favorable prognosis." (PMID 37461124, 2023). "In the differential diagnosis between sarcomatoid carcinoma (SC) and sarcomatoid mesothelioma (SM), we aimed to investigate the role of Claudin-4 and BAP1, a panel recently used to distinguish conventional carcinoma from epithelioid mesothelioma." (PMID 36673059, 2023). "Demonstration of loss of BAP1 or MTAP by immunohistochemistry, or CDKN2A homozygous deletion by FISH, is valuable in establishing the diagnosis of epithelioid mesothelioma." (PMID 36552912, 2022).
hereditary cancer syndrome (11 papers, 2017 to 2026). "The BRCA1–associated protein 1 (BAP1) gene, located on chromosome 3p21.1, is a tumour suppressor gene, and germline BAP1 mutations have been found in association with hereditary cancer syndrome." (PMID 28978163, 2017). "Moreover, we discovered a novel hereditary cancer syndrome characterized by a very high risk of MM and other cancers, caused by mutations in the tumor suppressor gene BRCA1 associated protein-1 (BAP1)." (PMID 28298211, 2017).
malignant peritoneal mesothelioma (11 papers, 2015 to 2025). An aggressive malignant mesothelioma that arises from the peritoneum. "Proteomic data from malignant peritoneal mesothelioma showed BAP1-deficient tumors characterized by an inflammatory TIME and immune checkpoint activation." (PMID 38987362, 2024). "Extensive workup for almost 2 months finally leads to the diagnosis of primary malignant peritoneal mesothelioma based on immunohistochemical analysis of loss of BAP1 gene." (PMID 36518655, 2022). "Immunohistochemistry, including markers such as calretinin, WT1, and BAP1, plays a pivotal role in confirming the diagnosis and differentiating malignant peritoneal mesothelioma from metastatic adenocarcinoma." (PMID 41147025, 2025). "Interestingly, BAP1 alterations have recently been shown to be correlated with perturbed immune signaling in malignant peritoneal mesothelioma." (PMID 36428720, 2022). "Further, it was shown that loss of 5-hmC can be an additional valuable marker, alongside BAP1 and MTAP immunostains, for distinguishing diffuse malignant peritoneal mesothelioma from reactive mesothelial hyperplasia in peritoneal biopsies." (PMID 37834158, 2023). "Recently, pediatric malignant peritoneal mesothelioma cases have been genetically studied, with alterations observed in ALK, EWSR1, FUS1, YY1, or in AURKA, AURKC, HLA-1B, ZNF-217, OR5F1, and MEN1 genes, but not in BAP1." (PMID 40725095, 2025).
prostate carcinoma (11 papers, 2015 to 2025). A carcinoma that arises from epithelial cells of the prostate gland. "Others reported that high BAP1 expression is associated with prostate cancer development and progression." (PMID 40136571, 2025). "We used a tissue microarray of 17,747 individual prostate cancer samples linked with comprehensive pathological, clinical and molecular data and studied the immunohistochemical expression of BAP1." (PMID 31903168, 2019). "In conclusion, this study shows that BAP1 up regulation is linked to prostate cancer progression and aggressiveness." (PMID 31903168, 2019). "Targeting BAP1 or its associated signaling pathways may hold promise for developing more effective treatment strategies for prostate cancer patients." (PMID 40136571, 2025). "In addition, we investigated whether the EMT regulation by BAP1 is implicated inthe migration and invasiveness of prostate cancer cells." (PMID 32422649, 2020). "However, BAP1 mutation has rarely been identified in prostate cancer (Jeet al., 2012)." (PMID 32422649, 2020). "However, BAP1 is rarely mutated in prostate cancers (Jeet al., 2012)." (PMID 32422649, 2020). "The study aims to explore the involvement of BAP1 protein expression in prostate cancer lethality and uncover the molecular mechanisms behind its tumor suppressive effects." (PMID 40136571, 2025). "Recent findings show that BAP1 suppresses prostate cancer progression by deubiquitinating and stabilizing PTEN, inhibiting the PI3K-AKT-mTOR pathway and suppressing trophoblastic EMT." (PMID 40136571, 2025). "In prostate cancer, we found contradictory data about the role of BAP1 expression in the disease’s pathogenesis and clinical outcomes." (PMID 40136571, 2025). "Understanding the role of BAP1 in prostate cancer is not only important for unraveling the molecular mechanisms underlying the disease but also for identifying novel therapeutic targets." (PMID 40136571, 2025). "BRCA1-associated protein 1 (BAP1) expression significance has been observed in various cancers, including prostate cancer." (PMID 40136571, 2025). "Then, to characterize BAP1 function in thedevelopment of prostate cancer, we established a stable BAP1-knockdown in PC3and DU145 cell lines using BAP1 specific shRNAs." (PMID 32422649, 2020). "To address the BAP1 function with respect to the progression of prostate cancer,we compared the mRNA levels of BAP1 in normal prostate samples (n = 52) andprostate cancer samples (n = 497) using data from the TCGA dataset." (PMID 32422649, 2020). "Kaplan-Meier analysis of atotal of 492 patients with prostate cancer showed that patients with high BAP1expression had worse disease-free survival compared with that of patients withrelatively low BAP1 expression (p < 0.01, log-rank test)." (PMID 32422649, 2020). "The TCGA dataset analysissuggested that high BAP1 expression is inversely correlated with disease-freesurvival in the context of prostate cancers." (PMID 32422649, 2020). "Analysis of The Cancer Genome Atlas (TCGA) dataset showed that prostate cancer patients express high levels of BAP1 mRNA." (PMID 32422649, 2020). "On analyzing the TCGA dataset, we found high expression of BAP1 mRNA inpatients with prostate cancer." (PMID 32422649, 2020). "We also found stronger evidence for BAP1 in the joint analysis of breast and prostate cancer." (PMID 40073867, 2025). "We assessed the expression significance between BAP1 and prostate cancer patients’ outcomes." (PMID 40136571, 2025). "BAP1 expression was also correlated with other known genomic changes in prostate cancer." (PMID 40136571, 2025).
prostate carcinoma (continued). "Deubiquitinase BAP1 is an important tumor suppressor in several malignancies, but its functions and critical substrates in prostate cancer (PCa) remain unclear." (PMID 33155366, 2021). "Our findingsindicate that BAP1 functions as a tumor promoter and could serve as a potentialtarget for preventing prostate cancer." (PMID 32422649, 2020). "Herein, we investigated the tumor promoting function of BAP1 inthe context of prostate cancer." (PMID 32422649, 2020). "Thus, identification of the mechanismsunderlying the effect of BAP1 on the development of prostate cancer will providevaluable insights for the treatment of prostate cancer." (PMID 32422649, 2020). "Therefore, to further investigatethe tumor promoting activity of BAP1 in prostate cancer cells, we introducedBAP1 or the Ub hydrolase activity deficient BAP1 mutant (BAP1 C91S) in RWPE1cells." (PMID 32422649, 2020). "Incorporating BAP1 expression may have prognostic value in men affected by prostate cancer." (PMID 40136571, 2025). "Thus, results from the TCGA cohort studies suggest that BAP1 mighthave a tumor promoting ability during the progression of prostate cancer." (PMID 32422649, 2020). "Recent research has revealed that the expression level of NOTCH1, BAP1, and TNFSF11 is closely related to bone metastasis in prostate cancer." (PMID 38384328, 2024). "Next, we investigated clinical relevance by analyzing the expression levels of BAP1 and PTEN in clinical prostate cancer tissues." (PMID 33155366, 2021). "We had found that the BAP1 protein was expressed at very low levels in RWPE1, thenormal prostate cell line, relative to its expression in tumorigenic andmetastatic prostate cancer cells." (PMID 32422649, 2020). "BAP1 interacts indirectly with ERG, a key oncogene in prostate cancer." (PMID 40136571, 2025). "However, theinvolvement of BAP1 in the progression of prostate cancer has not been studieduntil recently." (PMID 32422649, 2020). "Importantly, the involvement of BAP1 in theprogression of prostate cancer has not been studied until recently." (PMID 32422649, 2020). "Studies on the expression and prognostic role of BAP1 in prostate cancer are currently lacking." (PMID 31903168, 2019).
kidney tumors (10 papers, 2017 to 2025). "In this study, using a sequencing approach, we analyzed the mutations of VHL, PTEN, and BAP1 in 24 renal tumor specimens." (PMID 37445575, 2023). "In our study, we investigated VHL, PTEN, and BAP1 genes and the sequencing of 24 samples of patients with renal tumors, revealing that VHL was mutated at a noticeable frequency (25%)." (PMID 37445575, 2023). "Consistent with prior studies highlighting the potential role of chromatin dysregulation in aggressive renal neoplasms, we frequently identified mutations in chromatin remodeling genes, particularly BAP1 and SETD2, both of which have often been associated with rhabdoid features in ccRCC." (PMID 40940841, 2025). "The VHL, PTEN, and BAP1 genes are often mutated in renal tumors." (PMID 37445575, 2023). "For BAP1, it had been proven that BAP1 served as a tumor suppressor, and the loss of BAP1 could result in enhanced mesenchymal-epithelial transition in kidney tumor cells." (PMID 33790054, 2021). "However, loss of BAP1 has also been reported to promote mesenchymal-epithelial transition in kidney tumours cells suggesting that its precise mode of function depends on the cell- and tissue-specific context." (PMID 34170818, 2021). "Only after combination with Pbrm1 or Bap1 conditional knockout can Vhl loss lead to kidney tumors." (PMID 30355451, 2018). "BAP-1 mutations, which have been associated with poor prognosis in ccRCC, were observed in 10% of tumors in the overall cohort, consistent with prior studies, and no differential expression was seen between the primary renal tumors versus sites of metastasis." (PMID 39007269, 2024). "In the present study, we investigated the expression of mRNA for BAP1 and PTEN genes in 24 renal tumor specimens." (PMID 37445575, 2023). "The expression of the BAP1 and PTEN genes was detected in all of the 24 primary kidney tumor tissue samples examined." (PMID 37445575, 2023). "In order to examine the expression pattern of mRNA expression in BAP1 and PTEN genes in human kidney tumor tissues, RT-PCR was performed on all of the samples collected for the study." (PMID 37445575, 2023). "The number of genes within a panel may be as few as six (e.g. BAP1, FH, FLCN, MET, SDHB, and VHL genes) though commercial genetic testing companies may offer larger gene panels (18–30 genes but including some for non-RCC kidney tumours;)." (PMID 38802529, 2024).